EGR2 (early growth response 2)
Diseases named in the same sentence as EGR2 in open-access papers (continued):
Sharing a sentence is not in itself a finding about the gene and the disease.
cannabis dependence (1 paper, 2023). Physical and psychological dependence on the drug cannabis. "Specifically, the e-cigarette solvent vapor propylene glycol (PG) downregulated EGR2 and ARC mRNA expression in frontal cortex, an effect which was reversed by nicotine (NIC) and THC, suggesting that PG could have a protective role against NIC and cannabis dependence." (PMID 38002516, 2023).
Cavernoma (1 paper, 2022). "P-S6, a downstream effector of AKT/mTOR, was no longer active in most of the adult cavernoma-like vascular lesions we observed in mice with mutant Pik3ca in cells having once expressed Egr2/Krox20." (PMID 36353506, 2022).
Cerebral ischemia (1 paper, 2014). Restriction of arterial blood supply to the brain associated with insufficient oxygenation to support the metabolic requirements of the tissue. "We previously reported that the protective activity of EPO in a model of cerebral ischemia was paralleled by an upregulation of synaptic plasticity genes, particularly early growth response 2 (EGR2)." (PMID 24672526, 2014).
chronic lymphocytic leukemia (1 paper, 2024). "In patients with advanced chronic lymphocytic leukemia, recurrent mutations within EGR2 have been associated with poor prognosis." (PMID 38911380, 2024).
chronic myeloid leukaemia (1 paper, 2020). "The sensitivity accommodation by NFAT2 in chronic myeloid leukaemia, has been proved to have close relationship with the inducing expression of anergy-associated genes such as Egr2, Grail and Lck." (PMID 33023539, 2020).
chronic rhinosinusitis (1 paper, 2021). Chronic form of sinusitis. "Furthermore, EGR2 has shown the potential to retard the development of chronic rhinosinusitis induced by miR-150-5p in dendritic cells." (PMID 33980319, 2021).
coronary heart disease (1 paper, 2022). "Moreover, genes enriched in this pathway were related to an increased risk of coronary heart disease, such as NRG1, EGR2, and NOS1." (PMID 36032780, 2022).
Dystonia (1 paper, 2024). An abnormally increased muscular tone that causes fixed abnormal postures. "The YY1 gene encodes the zinc-finger TF protein yin and yang 1 that interacts with the dystonia-associated gene THAP1 and activates the myelination gene expression program centered on the TF EGR2, thus highlighting the crucial role of YY1 in central nervous system myelination." (PMID 38042508, 2024).
fungal infection (1 paper, 2020). "Our findings suggest that similar to amputation, fungal infection triggers neoblast proliferation by 6 hpi and it is preceded by ERK phosphorylation and the overexpression of the early wound response gene egr2." (PMID 33519792, 2020).
glioblastoma (1 paper, 2023). The most malignant astrocytic tumor (WHO grade IV). "LINC00470 and EGR2 mRNA expression gradually decreased with increasing concentrations of temozolomide in glioblastoma cells, and SOX4 expression was reduced in cells by temozolomide and LINC00470 knockdown." (PMID 36987665, 2023). "Four candidate transcription factors (GATAD1, TEAD4, IRF1, and EGR2) were finally obtained and were found to be considerably highly expressed in specimens of patients with glioblastoma according to the results of qRT‐PCR and western blot." (PMID 36987665, 2023). "Specifically, temozolomide treatment restricted cell invasion, migration, and angiogenesis but facilitated cell autophagy and apoptosis in glioblastoma via the inactivation of the LINC00470/EGR2/SOX4 axis." (PMID 36987665, 2023). "This study is dedicated to delve into the impact of the relationship between temozolomide and the LINC00470/EGR2/SOX4 axis on glioblastoma progression, thus presenting a fresh theoretical basis for the treatment of glioblastoma with temozolomide." (PMID 36987665, 2023). "Conclusively, temozolomide repressed glioblastoma progression by repressing the LINC00470/EGR2/SOX4 axis." (PMID 36987665, 2023). "LINC00470 expression and the predicted downstream transcription factor early growth response 2 (EGR2) were detected in the collected brain tissues from glioblastoma patients." (PMID 36987665, 2023). "Temozolomide repressed glioblastoma progression by repressing the LINC00470/EGR2/SOX4 axis." (PMID 36987665, 2023). "Collectively, temozolomide might repress cell proliferation, migration, invasion, and angiogenesis in glioblastoma through the disruption of the LINC00470/EGR2/SOX4 axis." (PMID 36987665, 2023). "This study further ascertained whether the regulation of temozolomide on cell apoptosis and autophagy in glioblastoma also involved the LINC00470/EGR2/SOX4 axis." (PMID 36987665, 2023). "Collectively, temozolomide might affect glioblastoma survival by suppressing LINC00470‐modulated EGR2." (PMID 36987665, 2023). "Overall, temozolomide treatment might block the LINC00470/EGR2/SOX4 axis to constrain glioblastoma growth in vivo." (PMID 36987665, 2023). "Bioinformatics analysis and experiments initially revealed that LINC00470 might exhibit regulatory effects in glioblastoma via EGR2 during temozolomide treatment." (PMID 36987665, 2023). "LINC00470 and EGR2 were highly expressed in brain tissues of glioblastoma patients." (PMID 36987665, 2023). "Taken together, temozolomide may restrain the malignant behaviors of glioblastoma by dampening the LINC00470/EGR2/SOX4 axis." (PMID 36987665, 2023). "Therefore, we hypothesized that temozolomide may delay the development of glioblastoma by inhibiting the transcriptional activation of SOX4 through LINC00470‐regulated EGR2." (PMID 36987665, 2023). "This study illustrated that temozolomide suppressed cell proliferation, migration, invasion, and angiogenesis, but accelerated cell apoptosis, autophagy in glioblastoma, as well as restricted tumor growth in vivo, by disrupting the LINC00470/EGR2/SOX4 axis." (PMID 36987665, 2023). "In addition, our data also revealed that EGR2 and LINC00470 expression decreased with the elevation of temozolomide concentration in glioblastoma cells." (PMID 36987665, 2023). "Moreover, EGR2 overexpression nullified the inhibitory effects of temozolomide treatment and LINC00470 knockdown on glioblastoma cell malignant behaviors." (PMID 36987665, 2023). "Altogether, temozolomide treatment might also facilitate apoptosis and autophagy of glioblastoma cells in vivo and in vitro by blocking the LINC00470/EGR2/SOX4 axis." (PMID 36987665, 2023).
glomerulonephritis (1 paper, 2022). A renal disorder characterized by damage in the glomeruli. "A previous study has shown that EGR2-/-B6 mice had increased IgG deposition in kidney and developed severe glomerulonephritis with the production of proteinuria." (PMID 35784356, 2022).
hamartoma (1 paper, 2022). A benign and excessive tumor-like growth of mature cells and normal tissues which grow in a disorganized pattern. "We have observed that benign vascular and/or hamartoma-like tumors arise postnatally in mice expressing constitutively active Pik3ca in a mosaic fashion, in cells having expressed the Krox20/Egr2 or Sox10 transcription factors." (PMID 36353506, 2022).
Hirschsprung disease (1 paper, 2022). Hirschsprung disease (HSCR) is a congenital intestinal motility disorder that is characterized by signs of intestinal obstruction due to the presence of an aganglionic segment of variable extent in the terminal part of the colon. "In Hirschsprung's disease, EGR2 may mediated the downregulated miR-140-5p to promote apoptosis in SH-SY5Y cells." (PMID 35971091, 2022).
hyperglycaemia (1 paper, 2020). "In fact, regulation of both, CCL2 and EGR2 mRNA expression, by higher concentrations of glucose was previously demonstrated on the model of THP1 macrophages and on PBMC in newly diagnosed pediatric patients with T1DM and T2DM suffering from hyperglycaemia." (PMID 33658980, 2020).
injury (1 paper, 2024). Damage inflicted on the body as the direct or indirect result of an external force, with or without disruption of structural continuity. "In conclusion, our findings elucidate the crucial role of EGR2 promoter antisense RNA (Egr2-AS) in modulating chromatin architecture and transcriptional regulation in Schwann cells following nerve injury." (PMID 39595160, 2024).
lung diseases (1 paper, 2023). "During symptomatic lung diseases, leptin is the main stimulator of LCK and EGR2 genes, which exacerbates inflammation and activates monocytes, respectively." (PMID 37408184, 2023).
metastatic tumor (1 paper, 2013). "We do not observe inverse correlation with the expression of previously identified miR-150 targets P2RX7 or EGR2 in our primary/metastatic tumor data." (PMID 23554878, 2013).
Myocardial fibrosis (1 paper, 2022). "However, the effect of EGR2 on scar formation and myocardial fibrosis after MI should be focused in the future." (PMID 35971091, 2022).
nonalcoholic fatty liver disease (1 paper, 2020). "Thus, we need to further investigate whether CPO-induced CD133 degradation affects EGR2 and apolipoprotein B expression levels, to overcome nonalcoholic fatty liver disease." (PMID 32397206, 2020).
Obesity (1 paper, 2016). Accumulation of substantial excess body fat. "Its anti-obesity action involves the inhibition of Egr2, C/EBPs, and PPARγ pathways in adipose tissues." (PMID 27063434, 2016). "In summary, this work demonstrated that B. pilosa and GHT suppressed adipogenesis and lipid content in adipocytes and/or animals via the down-regulation of the Egr2, C/EBPs and PPARγ pathways, suggesting a novel application of B. pilosa and GHT against obesity." (PMID 27063434, 2016).
Oral squamous cell carcinoma (1 paper, 2012). "Oral squamous cell carcinoma cells transfected with miR-100 may modify the expression of a number of oncogenes including ID1, EGR2, MMP13, and FGFR3." (PMID 23173870, 2012).
osteoporosis (1 paper, 2023). A condition of reduced bone mass, with decreased cortical thickness and a decrease in the number and size of the trabeculae of cancellous bone (but normal chemical composition), resulting in increased fracture incidence. "It upregulates the expression of the RNAKL repressor Id2, which was also demonstrated in female patients with osteoporosis whose serum IL-27 levels were reduced along with decreased Egr2 expression, suggesting a potential new anti-osteoporosis treatment strategy." (PMID 37475866, 2023).
pancreatic cancer (1 paper, 2024). "In addition, in xenograft models of pancreatic cancer, EGR2 gene silencing enhanced the anti-tumor potency of exhausted NK cells, leading to augmented tumor control, reduced tumor growth, decreased PD-1 expression, and the restoration of the cytotoxic potential of exhausted NK cells." (PMID 38637625, 2024).
periodontitis (1 paper, 2023). An acute or chronic inflammatory process that affects the tissues that surround and support the teeth. "In an experimental thioglycolate periodontitis model, Egr2 and Cebpb were required for macrophage activation." (PMID 36901771, 2023).
peritonitis (1 paper, 2018). Inflammation of the peritoneum (tissue that lines the abdominal wall and covers most of the organs in the abdomen). "On day 4 of thioglycollate-induced peritonitis, adoptively transferred DsRed+F4/80+ macrophages transfected with control siRNA upregulated MHC class II and CD86, while macrophages with siRNA for Egr2 had a significantly lower level of expression of these molecules." (PMID 30443252, 2018). "During thioglycolate-induced peritonitis, adoptively transferred macrophages with Egr2 knockdown failed to become activated as determined by upregulation of MHC class II and CD86." (PMID 30443252, 2018).
renal carcinoma (1 paper, 2024). A carcinoma arising from the epithelium of the renal parenchyma or the renal pelvis. "For example, EGR2 can drive renal cancer occurrence and metastasis by enhancing S1PR3 mRNA stability." (PMID 38911380, 2024).
status epilepticus (1 paper, 2016). Status epilepticus is defined as a continuous seizure lasting more than 30 min, or two or more seizures without full recovery of consciousness between any of them. "Kainic acid induces recurrent seizures, and the selected time point (i.e., 6 h) after the induction of status epilepticus enabled us to observe not only late-response genes but also early-response genes (e.g., Fos, JunB, FosB, Egr2, Egr4)." (PMID 25636686, 2016).
steatosis (1 paper, 2024). Increased lipid within the cytoplasm of cells. "The absence of Egr2 did not change the degree of inflammation or steatosis." (PMID 38831027, 2024).
substance abuse (1 paper, 2025). The use of a drug for a reason other than which it was intended or in a manner or in quantities other than directed. "Furthermore, transcription factors Nr4a1 and Egr2 have been reported to play important roles in mediating the neurobiology and behavioral consequences of substance abuse, including METH." (PMID 41002437, 2025).
Tinnitus (1 paper, 2023). Tinnitus is an auditory perception that can be described as the experience of sound, in the ear or in the head, in the absence of external acoustic stimulation. "Meanwhile, down-regulated genes between the tinnitus and the control group were Car3, Egr2, Bcl6b, C1qtnf12, Cartpt, LOC108348062, Nr4a3, Gprc5a, LOC103690128, and Angptl6." (PMID 37190538, 2023). "The expressions of Fos (p < 0.05), Nr4a1 (p < 0.01), Nr4a3 (p < 0.05), Egr2 (p < 0.01), and Egr3 (p < 0.05) were significantly decreased in the tinnitus group compared to the non-tinnitus group." (PMID 37190538, 2023).
trichothiodystrophy (1 paper, 2024). Trichothiodystrophy or TTD is a heterogeneous group disorders characterized by short, brittle hair with low-sulphur content (due to an abnormal synthesis of the sulfur containing keratins). "A quantitative lack of EGR2 could contribute to the reduced immune response often found in trichothiodystrophy patients." (PMID 39055713, 2024).
triple-negative breast carcinoma (1 paper, 2023). An invasive breast carcinoma which is negative for expression of estrogen receptor (ER), progesterone receptor (PR), and human epidermal growth factor receptor 2 (HER2). "Additionally, an inverse effect is observed on the expression of its different target mRNAs, the effect being clearer for PTEN and EGR2, which are downregulated in triple-negative breast cancer samples." (PMID 36980175, 2023).
Wilms tumor (1 paper, 2015). An embryonal neoplasm characterized by the presence of epithelial, mesenchymal, and blastema components. "The up-regulated EGR2 was found to be involved in overexpressing human embryonic kidney cells, which is indirectly associated with Wilms’ tumors." (PMID 26283601, 2015).
tumor (62 papers, 2005 to 2025). "We found that deficiency of Egr2 and 3 in T cells resulted in enhanced tumour growth and fewer TILs in mouse models." (PMID 36342511, 2023). "Using mouse models, we found that Egr2/3 were co-expressed with multiple checkpoint regulators in a proportion of TILs and deficiency of Egr2/3 in T cells resulted in aggressive tumour growth." (PMID 36342511, 2023). "In cancer patients, we found that TCF7, a signature gene for stem cell like exhausted T cells, was more highly expressed in PBMCs than in tumour cells, whereas Egr2 expression was specifically associated with the TME." (PMID 36342511, 2023). "Krox20/EGR2 is a zinc-finger transcription factor associated with hindbrain development, neuromyelin formation and tumor suppression." (PMID 34957116, 2021). "We also observed significant upregulation of genes encoding components of the NFAT/AP-1 signaling pathway heterodimers Junb and Fos, as well as NFAT associated transcription factors Egr1 and Egr2, and Tox in both unstimulated and tumor stimulated A1R CAR T cells." (PMID 40610421, 2025). "Deficiency of Egr2 and 3 in T cells resulted in excessive tumour growth." (PMID 36342511, 2023). "However, these researchers did not evaluate the role TGF-β plays in their model of tumorigenesis and therefore future research will be directed identifying how loss of SFRP1 together with TGF-β1, EGR2 upregulation, and additional tumor initiating pathways promote mammary carcinogenesis." (PMID 28687085, 2017). "Other key upstream regulators upregulated by 433‐3β treatment are EGR2 and Mag1, an apoptosis inducer and tumor suppressor, respectively." (PMID 40007440, 2025). "Both qRT-PCR and Western blot analyses revealed significant upregulation of SLC16A3 and downregulation of EGR2 in tumor tissues compared to adjacent normal tissues, which was corroborated by immunohistochemistry." (PMID 41583466, 2025). "In particular, our in vivo model of NK cell exhaustion reveals that gene silencing of Egr2 empowers NK cells to effectively control tumor growth and enhance NK cell effector functions for improved tumor lysis and clearance." (PMID 38637625, 2024). "A significant reduction of tumor volume and growth rate was observed in mice treated with EGR2 siRNA-NP vs NS siRNA-NP." (PMID 38637625, 2024). "Some researches have found that EGR2 is the target gene of miR-25 that can promote the proliferation of cancer cells, and knocking down EGR2 will promote the proliferation and spread of tumor tissues." (PMID 38329437, 2024). "Another GRN had high activity for IRF2, along with NFATC1/2 and EGR2, consistent with our recent report of tumor–intrinsic inflammatory JAK/STAT signaling and inflammatory programs driving lineage plasticity (labeled as IRF2+ Inflam)." (PMID 38645034, 2024). "Following EGR2 silencing, tumor lysis improved dramatically to levels similar to the cytolysis displayed by the responsive cells (Fig. EV5A)." (PMID 38637625, 2024). "Functional ex vivo analyses showed high degranulation in NK cells derived from mice that received Egr2 siRNA encapsulated nanoparticles directly linking NK cell activity to reduced tumor growth." (PMID 38886578, 2024). "To determine the potential of NK cell activation by targeting EGR2, we analyzed the cytolysis of tumor cells by anergic NK cells gene silenced for EGR2." (PMID 38637625, 2024). "Collectively, the in vivo data demonstrate that EGR2 siRNA-NP-treated NK cells exhibit superior anti-tumor activity over the control group, NS siRNA-NP-treated NK cells." (PMID 38637625, 2024). "Anergic NK cells treated with Egr2 siRNA exhibited increased cytotoxic potential as evidenced by improved tumor control, indicating a reversal of the dysfunctional state." (PMID 38886578, 2024). "Overall, the role of the EGR2 gene in tumor development and progression is complex and can vary depending on the specific context and tumor type." (PMID 38911380, 2024).